MPO (myeloperoxidase)
Diseases named in the same sentence as MPO in open-access papers (continued):
Sharing a sentence is not in itself a finding about the gene and the disease.
Autoimmunity (continued). "However, it promoted macrophage recruitment to the inflamed glomerulus and inhibited the generation of MPO-ANCA whilst not influencing T cell autoimmunity." (PMID 29315316, 2018). "One hypothesis is that hydralazine decreases DNA methyltransferase expression and induces autoimmunity by inhibiting extracellular signal-regulated kinase (ERK) pathway signaling and that may be responsible for disrupting the suppression of proteinase 3 (PR3) and MPO." (PMID 32290867, 2020). "Although it is not known how autoimmunity to MPO is generated in humans, evidence from animal studies shows that activation of myeloid DCs by NETotic, but not apoptotic or necrotic, neutrophils can result in the generation of MPO-specific autoimmunity and development of renal vasculitis." (PMID 26904693, 2016). "It has been suggested that the induction of ANCA in infectious diseases, more specifically in SBE, may occur through nonspecific B-cell activation or autoimmunization after the release of PR3 or MPO from neutrophils, and PR3/C-ANCA is the most common ANCA type." (PMID 23268737, 2012). "In early anti-MPO GN (day 20), neither anti-TNF-α nor anti-IFN-γ mitigated kidney injury, consistent with Th17-driven autoimmunity at this stage." (PMID 40735321, 2025). "This was also observed in our models of anti-MPO GN, where OVA-immunized mice (without autoimmunity to MPO) had substantially more DNase I protein expression than untreated mice, and exogenous DNase I partially restored this level in the kidney." (PMID 40632882, 2025). "Among all the antibodies with differences, 12 IgG antibodies against Jo-1, SSB, PL-12, PM/scl100, Scl-70, TIF1γ, β-actin, MPO, TTG, AQP4, calprotectin, and CRP were more abundant in patients with autoimmunity than in those without (p < 0.05)." (PMID 38634985, 2024). "The case presented is about an RPGN in a young patient with no significant medical history, nor a previous significant clinical history of autoimmune conditions, presenting dialytic urgency with negative immunological studies, except for positive ANCA-P / MPO." (PMID 33501927, 2022). "A major deficiency of the hypothesis that ANCA induced renal disease was the fact that the key autoantigens, MPO and PR3 were not expressed in the kidney, the major organ damaged by autoimmunity to these antigens." (PMID 33790907, 2021). "A study using a mouse MPO model showed that the pathology was improved by disodium cromoglycate (DSCG), known as an MC stabilizer, whereas DSCG did not affect the development of MPO autoimmunity of KitW/W-v mice." (PMID 34067047, 2021).
breast carcinoma (53 papers, 2009 to 2025). "In breast cancer patients an increased serum-MPO level was shown, and the risk of developing breast cancer increased with higher endogenous levels of MPO31." (PMID 40652059, 2025). "This study investigates the impact of lidocaine (combined with sevoflurane or propofol anesthesia ) during breast cancer surgery inhibits the expression of biomarkers associated with metastasis and recurrence (specifically H3Cit, NE, MPO, MMP-9 and VEGF-A)." (PMID 38678209, 2024). "The high tumor infiltration of MPO-expressing cells in colorectal and breast cancers is associated with a significant improvement in prognosis." (PMID 35912260, 2022). "A recent study has shown that infiltration by myeloperoxidase-positive neutrophils is an independent prognostic factor associated with a better overall survival in breast cancer." (PMID 33216733, 2020). "Up to 2010, a meta-analysis gave a systematic review into the association between MPO-463G > A polymorphism and cancer risk, including breast cancer, leukemia, and lung cancer." (PMID 28764808, 2017). "Previous studies have found that low-activity MPO genotypes are associated with poor survival in esophageal and breast cancer patients treated with chemotherapy." (PMID 24340057, 2013). "A large number of studies have reported the role of MPO G-463A polymorphism regarding breast-cancer risk." (PMID 23991124, 2013). "We therefore undertook a meta-analysis to evaluate the association between MPO G-463A polymorphism and breast cancer risk." (PMID 23991124, 2013). "Under the recessive model, there was a significant association between MPO G-463A polymorphism and breast-cancer risk (OR = 0.57, 95% CI 0.34–0.93, p = 0.025)." (PMID 23991124, 2013). "Characteristics of the studies of MPO-G463A polymorphism and its association with breast cancer stratified by menopausal status and antioxidant intake." (PMID 22427832, 2012). "An important modifier in the relationship between MPO genotype and breast cancer risk is consumption of fruits and vegetables." (PMID 22427832, 2012). "Our meta-analysis implicates that menopausal status and intake of antioxidants modified the risk associated with breast cancer risk of women who carried the low activity AA genotype of MPO-G463A polymorphism." (PMID 22427832, 2012). "Characteristics of the studies of MPO-G463A polymorphism and its association with breast cancer according to menopausal status." (PMID 22427832, 2012). "Characteristics of the studies of MPO-G463A polymorphism and its association with breast cancer stratified by antioxidant and vitamin-carotenoid intake." (PMID 22427832, 2012). "Based on a homogeneous Caucasian population, the MPO G463A polymorphism places post-menopausal women at risk for breast cancer, where this effect is modified by diet." (PMID 22427832, 2012). "Here we investigated the breast cancer risk associated with MPO-G463A polymorphism status in ethnically homogenous Caucasian women." (PMID 22427832, 2012). "Accumulating evidence also suggests association of MPO-G463A with breast cancer development although discrepancies exist." (PMID 22427832, 2012). "To investigate the association of TANs and MPO-expressing cells on total survival time from initial breast cancer diagnosis, we next performed Kaplan Meier Log Rank tests, using the time scale OS as measured in time from initial breast cancer diagnosis." (PMID 40652059, 2025). "However, using a different cohort with primary breast cancer at earlier stages, we recently showed that a subpopulation of MPO+ neutrophils were associated with worse prognosis in breast cancer patients." (PMID 40652059, 2025). "Furthermore, a meta-analysis involving 1979 patients, predominantly with breast cancer (99%) receiving anthracycline treatment, demonstrated that elevated MPO levels after treatment were associated with an increased risk of cardiotoxicity." (PMID 37886969, 2023).
breast carcinoma (continued). "Furthermore, increased MPO activity is reported to be associated with early‐stage development of lung and breast cancer and drives tumour metastasis." (PMID 37699574, 2023). "In addition, the serum MPO-DNA complex level was confirmed to monitor the HER2 inhibitor-associated vasculitis activity from a prospective cohort of breast cancer." (PMID 36859358, 2023). "Also, baseline high MPO blood levels were associated with worse myocardial injury after ANT chemotherapy for breast cancer, as reflected by TnI increase, which was prevented by carvedilol." (PMID 35087624, 2022). "In a multicenter study with a small sample size of 78 patients with breast cancer undergoing doxorubicin and trastuzumab therapy, an early increase in ultrasensitive troponin I (TnI) and myeloperoxidase (MPO) levels offered additive information on the risk of cardiotoxicity." (PMID 36005423, 2022). "Moreover, other markers of NETosis, such as MPO and NE, have already been associated with tumor progression in colorectal cancer, breast cancer, gastric adenocarcinoma." (PMID 35449078, 2022). "In human breast cancer tissue, MPO-positive neutrophils were observed in up to 16% of cases, and were associated with an enhanced prognosis, probably owing to the activation of M2-like macrophages induced by MPO-positive neutrophils." (PMID 32726950, 2020). "Hence, we conducted a meta-analysis to explore the association between MPO G-463A polymorphism and breast cancer risk." (PMID 23991124, 2013). "Genetic polymorphism of MPO and breast cancer risk in post-menopausal women." (PMID 23991124, 2013). "Genetic polymorphism of MPO and breast cancer risk in pre-menopausal women." (PMID 23991124, 2013). "On the other hand, post-menopausal women with low levels of MPO activity who consumes low antioxidants sources are likely to have increased levels of oxidative stress which may significantly raise breast cancer risk in this group." (PMID 22427832, 2012). "Breast cancer susceptibility may be modulated partly through polymorphisms in oxidative enzymes, one of which is myeloperoxidase (MPO)." (PMID 22427832, 2012). "It has been shown that post-menopausal women with reduced levels of MPO activity who consume low antioxidants are likely to have increased levels of oxidative stress which may significantly raise breast cancer risk." (PMID 22427832, 2012). "Results of the meta-analysis for MPO-G463A polymorphism and breast cancer risk." (PMID 22427832, 2012). "Therefore, we hypothesized that lidocaine (combined with sevoflurane or propofol anesthesia) during breast cancer surgery inhibits the expression of biomarkers associated with metastasis and recurrence (specifically H3Cit, NE, MPO, MMP-9 and VEGF-A)." (PMID 38678209, 2024). "In this study, we perform a meta-analysis to evaluate the association between the MPO-G463A variant and risk of breast cancer, also taking into consideration the potential modifying influences of menopausal status, antioxidant and vitamins/carotenoid intake of breast cancer and healthy women." (PMID 22427832, 2012). "In these tumors, MPO that clearly promotes progression of breast cancer in vivo30may be involved in promoting metastases also in human." (PMID 40652059, 2025). "By utilizing ELISA, MPO: DNA was detected in the patient’s serum, and we also identified that, in comparison with the healthy population, there were greatly increased expression levels of MPO: DNA in the serum of breast cancer patients." (PMID 40148973, 2025). "In adult breast cancer patients, Myeloperoxidase (MPO), an enzyme released during oxidative stress and extracellular matrix degradation, has been correlated with a decline in left ventricular ejection function (LVEF)." (PMID 41304849, 2025). "Our findings are in contradiction to a previous study regarding MPO as a biomarker for improved survival in breast cancer patients." (PMID 40652059, 2025).
breast carcinoma (continued). "In summary, when evaluating OS time as measured from initial breast cancer diagnosis, high amounts of MPO+ cells and particularly of CD15+MPO+ TANs in PT, was associated with a worse prognosis." (PMID 40652059, 2025). "Our study demonstrated that the addition of lidocaine effectively inhibits the increase of NETosis markers (MPO and NE) induced by breast cancer surgery." (PMID 38678209, 2024). "In summary, our study demonstrated that the addition of lidocaine effectively inhibits the increase of NETosis markers (MPO and NE) induced by breast cancer surgery." (PMID 38678209, 2024). "In a multicenter cohort study, hs-cTnI and MPO, along with LVEF, were identified as predictors of cardiotoxicity risk in 78 breast cancer patients who received DOX and trastuzumab for 3 months." (PMID 38676836, 2024). "We have previously shown that increased MPO can produce favourable conditions for tumour progression, eliciting a pro‐fibrogenic and pro‐angiogenic tumour microenvironment in a mouse model of breast cancer." (PMID 37699574, 2023). "MPO levels were significantly elevated in HER2+ breast cancer patients by 3 months of treatment and were significantly associated with cardiotoxicity during the entire treatment course of doxorubicin/trastuzumab with HR = 1.37 (95% CI (1.11–1.69); p = 0.02)." (PMID 37444400, 2023). "Specifically, MPO has been shown to be predictive of cardiotoxicity in breast cancer patients receiving doxorubicin and trastuzumab." (PMID 37886969, 2023). "Increased plasma levels of the neutrophil-derived enzyme myeloperoxidase (MPO) were recently shown to predict cardiotoxicity in DOX-treated breast cancer patients." (PMID 37656254, 2023). "The administration of exogenous MPO in a mouse breast cancer model stimulated a significant increase in tumour size compared to control animals." (PMID 37513924, 2023). "The expression of serum MPO-DNA was validated as a predictor of liver metastasis for early-stage breast cancer patients." (PMID 36859358, 2023). "In colorectal and breast cancer patients, measurement of NET-associated products including citH3 and MPO in the blood cfDNA is more specific than cfDNA alone." (PMID 36341351, 2022). "Fourth, theoretically being more inflamed, patients with breast cancer disease would have a greater value of baseline MPO." (PMID 35087624, 2022). "Higher expression of FVIII (hematopoietic markers for megakaryocyte), CD117 (erythroid marker) and MPO (granulopoietic marker) was observed in the samples from mice developing breast cancer in comparison to controls." (PMID 32191918, 2020). "Higher levels of CXC-receptor and ligands in chemotherapy-resistant breast cancer patients suggest the recruitment of a higher number of neutrophils, characterized by the MPO gene, to the tumor sites of chemotherapy-resistant patients." (PMID 33049964, 2020). "Several reports are available about the relationship between breast cancer and increased serum MPO level as compared to control groups." (PMID 29669993, 2018). "We describe here the in depth characterization of T47D breast cancer cells as a superior recombinant expression system for the study of the biosynthetic processing, endocytic trafficking and lysosomal storage of myeloperoxidase." (PMID 26890638, 2016). "We report here that T47D breast cancer cells stably transfected with an MPO expression plasmid are able to efficiently replicate all of the processing steps that lead to formation of the mature MPO heterotetramer." (PMID 26890638, 2016). "Several studies have shown the possible involvement of MPO in the pathogenesis of breast cancer; however, the conclusions are inconsistent." (PMID 23991124, 2013). "Although MPO is correlated with a better prognosis in different types of tumours such as breast cancer, the majority of studies have shown an important role for MPO in cancer progression." (PMID 23176085, 2012).
breast carcinoma (continued). "Whether MPO alone, or NETosis as such, mediates the mechanisms of action in relation to breast cancer metastasis and progression, needs further investigation." (PMID 40652059, 2025). "The results need to be validated in a larger cohort but suggests that MPO targeting strategies could be relevant in breast cancer patients with aggressive disease." (PMID 40652059, 2025). "Furthermore, MPO has been shown to promote progression of breast cancer both in vitro and in an in vivo model." (PMID 40652059, 2025). "It is therefore of importance to reveal whether MPO has a prognostic impact in breast cancer patients, especially in the TNBC group that would benefit from ICI treatment the most, but also in MBC patients." (PMID 40652059, 2025). "In summary, although they need to be validated in a larger cohort, the findings in our present study suggest that future clinical trials using immunotherapies targeting neutrophils and MPO should be focused on patients with particularly aggressive breast cancer and especially MBC patients." (PMID 40652059, 2025). "Elevated circulating levels of MPO were found in breast cancer patients that experienced cardiotoxicity, so MPO is now considered a promising biomarker for the early detection of anthracycline-related and anthracycline–trastuzumab cardiac dysfunction, based on the results of several studies." (PMID 38397436, 2024). "Similarly, another study showed higher serum levels of MPO at 3 months of treatment compared to the baseline (p < 0.05) in a multicenter cohort of 78 HER2+ breast cancer patients treated with adjuvant doxorubicin, taxanes, and trastuzumab." (PMID 37444400, 2023). "Moreover, the coexpression of PANX1 and MPO in basal-like breast cancer paraffin-embedded surgical specimens was also observed using immunofluorescence." (PMID 35884429, 2022). "Therefore, we evaluated the effect of carvedilol on MPO and Gal-3 blood levels among women with breast cancer undergoing ANT chemotherapy that attended CECCY trial." (PMID 35087624, 2022). "Similarly, the addition of exogenous MPO in a murine mammary tumor model stimulated significant increases in tumor size compared to control animals." (PMID 36293108, 2022). "Numerous studies have reported the role of MPO G-463A polymorphism in affecting the risk of breast cancer, but results differ and the genetic linkages have not always been replicated." (PMID 23991124, 2013). "Thus, in premenopausal women suffering from breast cancer, MPO acts as an efficient marker." (PMID 29669993, 2018). "MPO-463G > A polymorphism might have an effect in reducing the risk of digestive system cancer, but might not be a good predictor of lung cancer, breast cancer, and blood system cancers." (PMID 28764808, 2017). "In summary, our results indicated that MPO-G463A polymorphism might not be a good predictor of breast cancer risk, while menopausal status modifies a woman’s risk of breast cancer." (PMID 23991124, 2013). "We conclude that MPO-G463A polymorphism might not be a good predictor of breast-cancer risk, though menopausal status modified women’s risk of developing breast cancer." (PMID 23991124, 2013). "In addition, giving to the fact the level of MPO-containing neutrophils were high in breast tissue with or without cancer, we tend to believe that MPO-463G > A polymorphism could not predict breast cancer well." (PMID 28764808, 2017). "We report here two related breast cancer cell lines, T47D and MCF7, that when stably transfected with the MPO gene, generate the heterotetramer and store it in lysosomes with an efficiency approaching that of MPO-processing and storage in HL60 cells." (PMID 26890638, 2016). "The classifiers were able to distinguish normal tissue from breast cancer with a classification performance of AUC = 0.82 ± 0.04 with the proteins MIF, MMP-9, and MPO." (PMID 19476629, 2009).